CD4 (CD4 molecule)
Diseases named in the same sentence as CD4 in open-access papers (continued):
Sharing a sentence is not in itself a finding about the gene and the disease.
Hyperkeratosis (8 papers, 2002 to 2023). Hyperkeratosis is a histopathological term defining a thickened stratum corneum and may be present in many different skin conditions, with many possible overlaps. "IL-1β and IL-6 have been confirmed to promote the differentiation of CD4+T cells into Th17 cells, in which IL-17 is produced, and higher IL-17 levels recognized by keratinocytes leads to severe hyperkeratosis and inflammatory infiltration." (PMID 37111171, 2023). "Histological and immunohistochemical analyses of the skin from Dock8−/− AND Tg mice revealed acanthosis, hyperkeratosis and mild spongiosis with massive infiltration of CD4+ T cells and, to lesser extent, eosinophils." (PMID 28067314, 2017). "These hallmarks included epidermal acanthosis, spongiosis, hyperkeratosis, and parakeratosis, systemic type 2 cell expansion with a dramatic accumulation of CD4+ T cells, neutrophils, eosinophils and dermal mast cells, and elevation of serum IgE and TSLP levels." (PMID 24843010, 2014). "The total population of CD4, CD8 and B cells, in the tissue specimens, were evidently higher in moderate and severe dysplasia and SCC lesions compared with hyperkeratosis and mild dysplastic lesions." (PMID 11986779, 2002).
idiopathic CD4 lymphocytopenia (8 papers, 2013 to 2026). A rare primary immunodeficiency disorder characterized by persistent CD4 T-cell lymphopenia (less than 300 cells/B5L on multiple occasions) not associated with any other underlying primary or secondary immune deficiency. "Idiopathic CD4 lymphocytopenia (ICL) is a rare clinical disease with relative deficiency of CD4 T-cells in the absence of human immunodeficiency virus (HIV) 1 and 2 infections." (PMID 31623573, 2019).
lepromatous leprosy (8 papers, 2013 to 2024). A chronic communicable infection which is a principal or polar form of leprosy. "Hence, it appears that the development of ENL in patients with lepromatous leprosy is mainly associated with the decreasing frequency of CD4+Tregs being unable to balance the excessive immune activation via CD4+ T-cells." (PMID 28991896, 2017). "Our study found that PD-1 expressing CD4+CD25+FoxP3+ Treg cells were more prevalent in lepromatous leprosy and tuberculoid patients compared to healthy controls which is consistent with other studies." (PMID 37153623, 2023). "Simultaneously, presence of Th17 related cytokines (TGF-β, IL-6, IL-17 and IL-23) decreased the number of FoxP3+ Treg cells concomitantly increasing IL-17 producing CD4+ cells in lepromatous leprosy." (PMID 26751584, 2016). "Our studies find an increase in lineage specific CD4+ iTregs in lepromatous leprosy as compared to the limited form of borderline tuberculoid leprosy." (PMID 24454972, 2014). "The present investigation provides evidence for the increase of CD4+ CD25+ FOXP3+ iTreg cells in antigen stimulated PBMC cultures of anergic lepromatous leprosy patients." (PMID 24454972, 2014). "Hence, the finding of the imbalance of T-lymphocyte subpopulations (CD4+/ CD8+ ratio) in this study would support the initiation of ENL reaction in patients with lepromatous leprosy." (PMID 28991896, 2017). "Taken together the data provides evidence for increase in antigen induced iTregs in lepromatous leprosy which bear the signature markers of CD25 and FOXP3 in the CD4 lineage of T cells." (PMID 24454972, 2014). "Lepromatous leprosy patients showed significantly lower IFN-γ and higher IL-4 levels in culture supernatant and significantly low expression of IFN-γ and higher expression of IL-4 by CD4+ T cells than healthy individuals with or without antigenic stimulation." (PMID 30642265, 2019).
MALT lymphoma (8 papers, 2016 to 2025). An indolent, extranodal type of non-Hodgkin lymphoma composed of small B-lymphocytes (centrocyte-like cells). "CD4+ naive T-cells: Upregulated genes in MALT lymphoma were significantly enriched in pathways associated with ribosome function, PD-1 and PD-L1 signaling, Th17 cell differentiation, and antigen presentation pathways." (PMID 40078987, 2025). "The results indicated that the proportions of Tfh cells and CD4+ naive T-cells were greater in MALT lymphoma tissues, whereas the proportions of proliferating T-cells, Treg cells, and CD8+ Teff cells were relatively greater in IgG4-ROD tissues." (PMID 40078987, 2025). "Our findings have demonstrated that CD4+ T-cells play a crucial role in promoting the growth of MALT lymphoma." (PMID 40078987, 2025). "Through comparative analysis, we observed that naive CD4+ T-cells predominantly differentiate into Tfh cells in MALT lymphoma, whereas in IgG4-ROD, they are more likely to differentiate into Treg cells." (PMID 40078987, 2025). "CD4+ naive T cells in MALT lymphoma patients are highly likely to differentiate into follicular helper T cells, while in IgG4-ROD patients, CD4+ naive T cells are highly likely to differentiate into regulatory T cells." (PMID 41221279, 2025). "CagY predominantly drives Interferon-gamma (IFN-γ) and Interleukin-17 (IL-17) secretion by gastric CD4+ T cells from H. pylori-infected patients with low-grade gastric MALT lymphoma." (PMID 34502367, 2021). "Results: 22 of 158 CD4+ (13.9%) gastric clones from MALT lymphoma and three of 179 CD4+ (1.7%) clones from chronic gastritis recognized CagY." (PMID 34502367, 2021). "While 22 CD4+ (corresponding to 13.9%) of clones from MALT lymphoma showed antigen-induced proliferation, only three CD4+ clones (1.7% of the clones) from chronic gastritis were CagY-specific." (PMID 34502367, 2021). "Intergroup differential gene KEGG pathway enrichment results indicated that both the CD4+ T-cell and CD8+ Teff cell subpopulations in MALT lymphoma patients were significantly enriched in the PD-1/PD-L1 pathway, compared with those in IgG4-ROD patients." (PMID 40078987, 2025). "Pseudotime analysis revealed that CD4+ naive T-cells in MALT lymphoma patients were highly likely to differentiate into follicular helper T-cells, whereas, in IgG4-ROD patients, CD4+ naive T-cells were highly likely to differentiate into regulatory T-cells." (PMID 40078987, 2025). "Comparable numbers of clones were obtained from both cohorts: a total of 158 CD4+ and 17 CD8+ clones were obtained from the gastric biopsy specimens of MALT lymphoma." (PMID 34502367, 2021). "Indeed, higher Foxp3/CD4 cell ratios and the absolute number of Foxp3 cells in GML were previously found to be significantly higher in H. pylori eradication responders compared to non-responders, suggesting that Tregs have a function in regression mechanisms of MALT lymphoma." (PMID 26657504, 2016).
membranous nephropathy (8 papers, 2017 to 2026). "More recent study on HBV-associated membranous nephropathy revealed that the percentage of CD4+CXCR5+ follicular T helper (Tfh) cells was negatively correlated with the value of eGFR." (PMID 28274240, 2017). "Previous research has found that the number of T and B lymphocytes in the peripheral blood of patients with idiopathic membranous nephropathy is equivalent to that of healthy controls, but the CD4 +/CD8 + ratio is increased." (PMID 37974210, 2023). "Significantly higher frequency of CD4+/CXCR5+, CD4+/CXCR5+/ICOS+ and CD4+/CXCR5+/PD-1+ TFH cells, and higher serum levels of IL-17A, IFN-γ, IL-2, IL-10, IL-4 and IL-21 were detected in hepatitis B virus-associated membranous nephropathy patients compared to the healthy controls." (PMID 28770269, 2018). "Similar findings were observed in patients with membranous glomerulonephritis (MGN), in which OPN correlated with increased infiltration of macrophages, as well as CD4+ and CD8+ T cells." (PMID 31159229, 2019). "At present, there is no well-established mouse model that mimics membranous nephropathy, and technical limitations make the isolation of naïve CD4+ T cells from rats more challenging." (PMID 41491334, 2026). "The pathology showed features of early membranous glomerulonephritis negative for anti-phospholipase -A2-receptor (PLA2R) autoantibodies with focal T cell–rich crescent-like inflammation and acute glomerulocentricnephritis with T cells positive for CD3, CD4, and CD8." (PMID 30612580, 2019).
mood disorder (8 papers, 2018 to 2025). A cognitive disorder a disturbance in which the person's mood is hypothesized to be the main underlying feature. "Though the pathophysiology and treatment of mood disorder have been currently studied, emerging evidence points to unique role of CD4+ T cells in mood disorder, especially those caused by T. gondii infection." (PMID 37077528, 2023). "In this review, we explore the ability of T. gondii to cause alterations in CD4+ T cell numbers and function and the link between several important CD4+ T cells and mood disorders, including Tregs, Th1, Th2, and Th17 cells." (PMID 37077528, 2023). "Future studies are needed to unravel their specific roles in driving different CD4+ T cell subsets in the pathophysiology of mood disorders." (PMID 33921690, 2021). "We next focus on CD4+ T cell numbers and function during T. gondii infection and mood disorders." (PMID 37077528, 2023). "We therefore propose a reasonable hypothesis that inflammation has a positive effect on mood disorders and that CD4+ T cells may be involved in the pathogenesis of T. gondii -induced mood disorders by regulating and participating in immune inflammatory mechanisms." (PMID 37077528, 2023). "Despite the fact that DCs are master regulators of Th cell responses by using different strategies, studies unraveling the role of DCs in CD4+ Th cell regulation in mood disorders are still lacking." (PMID 33921690, 2021).
Multiple Organ Failure (8 papers, 2012 to 2024). A progressive condition usually characterized by combined failure of several organs such as the lungs, liver, kidney, along with some clotting mechanisms, usually postinjury or postoperative. "P, predictive value; e, natural logarithm; IFN-γ+ CD4+T cell number, number of IFN-γ+ CD4+ T cells per microliter; Cr, creatinine concentration(μmol/L); MOF, multiple organ failure." (PMID 33072617, 2020). "The expansion of CD4+ T cells and CD8+ T cells in response to HHV-6 reactivation seems to be of extreme importance in the development of multiple organ failure during the course of anticonvulsant HSR." (PMID 22666603, 2012). "Furthermore, it was shown that an increase in the content of activated effector T cells with CD4+CD25+CD127high phenotype has a significant negative correlation with multiple organ failure." (PMID 37034572, 2023). "By contrast, level of the peripheral CD4+CD25+CD127high Tregs showed a significant negative correlation with multiple organ failure in the early stage of AP, implying that activated effector T cells phenotyped as CD4+CD25+CD127 high may be an independent prognostic biomarker for SAP." (PMID 32266154, 2020).
Mycobacterium infection (8 papers, 2014 to 2025). Infections with bacteria of the genus Mycobacterium. "Immune control of Mycobacterium infections relies on a T helper 1 (Th1) immune response driven by CD4 T cells and functional proliferation and production of IFN-γ." (PMID 39815253, 2025). "IL-1 is known to induce and enhance memory-type immune responses (44, –, 46), whereas TNF-α protects against Mycobacterium infection and plays a functional role in CD4 and CD8 T cell responses to M. tuberculosis infection." (PMID 33692195, 2021). "Additionally, in the case of concomitant mycobacterium infection, the initiation of antituberculous therapy inhibits the immunosuppressive effect of CD4+ Th2, further exacerbating the inflammatory response." (PMID 25478257, 2014). "In addition, TNF-α has an immune regulatory function that controls Th1 cell activation and immunopathology following pulmonary mycobacterial infection, and it is also a negative regulator of CD4 and CD8 T-cell responses to lymphocytic choriomeningitis virus infection." (PMID 24676272, 2014). "A long-term immune response based on the presence of memory (CD44+ CD62LLow CD25−) CD4+ T and (CD44+ CD62LLow CD45R−) CD8+ Tcells is examined to determine protection from mycobacterium infection." (PMID 28224119, 2017).
myocardial ischemia (8 papers, 2012 to 2025). A disorder of cardiac function caused by insufficient blood flow to the muscle tissue of the heart. "For example, netrin-1 overexpression has been shown to suppress IL-6 and COX-2 expression, reduce Th1/Th2/Th17 cytokines from CD4+ T cells, and improve outcomes in models of kidney and cardiac ischemia." (PMID 40728980, 2025). "Although 70% of IL-17A is expressed by Th cells, the differentiation of naive CD4 + T cells into Th17 cells takes a long time and cannot produce a large amount of IL-17A in a process similar to myocardial ischemia." (PMID 37600023, 2023). "Taken together, our data suggest that trafficking of CD4+ TEM cells in response to acute myocardial ischemia may be orchestrated in an IP-10 – CXCR3 dependent manner controlling cardiac repair in AMI." (PMID 37426649, 2023). "In myocardial ischemia-re-perfusion injury, myocardial tissue in the damaged area is mainly infiltrated with CD4 + T cells as the main effector cells, which can infiltrate into the infarct area 2 min after re-perfusion and participate in sustained and stable myocardial injury." (PMID 37600023, 2023). "Altogether, this suggests an important role of CD4+CCR7+ T cells during early reperfusion and potentially myocardial ischemia/reperfusion injury." (PMID 23077561, 2012). "Therefore, various T lymphocyte sub-types have been widely studied, including NKT cells, TH17 cells, γδT cells, CD4 + T cells and CD8 + T cells, among which γδT cells play an important role in myocardial ischemia-re-perfusion injury." (PMID 37600023, 2023). "Reconstitution of immunodeficient Rag1−/− mice with Ifn-γ−/− CD4+ T cells did not recapitulate the detrimental effects of WT CD4+ T cells transfer in a transient myocardial ischemia model." (PMID 30687720, 2018).
neurosarcoidosis (8 papers, 2021 to 2025). A sarcoidosis that involves the nervous system. "Brain neurosarcoidosis is characterized by a mixed cellular infiltration composed by histiocytes, macrophages, both CD4 and CD8 T lymphocytes and B lymphocytes." (PMID 34215779, 2021). "We think, that a more systematic analysis of CSF CD4/CD8 T cell ratio is needed in larger cohorts of neurosarcoidosis and MS patients, to sharpen the picture and to clearly determine the best cut-off value and the respective sensitivity, specificity, PLR and NLR for neurosarcoidosis vs. MS." (PMID 37034091, 2023). "ScRNA-seq of CSF and blood cells from neurosarcoidosis participants, coupled with T and B cell receptor sequencing, revealed that unlike pulmonary sarcoidosis, which is driven by CD4 T cells, neurosarcoidosis showed an enrichment of CD8 T cell clonal expansion in the CSF." (PMID 40510352, 2025). "However, the combination of a CD4/CD8 T cell ratio ≥5 and elevated lymphocyte count in CSF increased the positive predictive value (57%) with a negative predictive value (88%) and a specificity of 95% for neurosarcoidosis." (PMID 37034091, 2023). "We have not analyzed CD4/CD8 T cell ratio in CSF, but an increase of CSF CD4/CD8 T cell ratio >5.0 has so far been found in 14–38% neurosarcoidosis patients and has been proposed as cut-off value to favor the diagnosis of neurosarcoidosis." (PMID 37034091, 2023).
obliterative bronchiolitis (8 papers, 2007 to 2023). "Bronchiolitis obliterans syndrome is also associated with increased levels of CD4+CD28− T cells compared to stable lung transplant patients." (PMID 25834833, 2015). "elegantly demonstrated that cGvHD pathology manifests in fibrosis and bronchiolitis obliterans and was associated with CD4+ as well as B220+ B cell infiltration and that germinal center B cell reactions occurring at onset of cGvHD seem to facilitate disease development." (PMID 36761159, 2022). "IL-17a is a pro inflammatory cytokine released by effector CD4+CD25+ cells under certain inflammatory diseases and associated with other forms of bronchiolitis obliterans." (PMID 34941793, 2021). "Contrary to these findings a newer study showed an increase of CD40L in CD4+CD28− T cells in bronchiolitis obliterans syndrome." (PMID 25834833, 2015). "The molecules 4-1BB and CTLA-4 are responsible for the production of cytotoxic T cells before or during graft rejection and OX40 and CD40L are important for proliferation and cytokine production of CD4+CD28− T cells in bronchiolitis obliterans syndrome." (PMID 25834833, 2015). "An upregulation of cytotoxic T-lymphocyte-associated protein 4 (CTLA-4 = CD152) was detected on CD4+CD28− T cells from healthy subjects and patients with bronchiolitis obliterans syndrome." (PMID 25834833, 2015). "Daughter progeny of T-cell clonal proliferations (which can develop into CD4+CD28null cells) comprise a very similar proportion of circulating CD4 T-cells (∼36%) among lung transplant recipients with severe lung damage due to obliterative bronchiolitis." (PMID 20126467, 2010). "Furthermore, a recently published study in a murine model of mice transplanted with human umbilical cord blood of cGVHD showed that IL26+CD26+CD4 T cell infiltration has the potential to play an important role in obliterative bronchiolitis." (PMID 35501858, 2022). "Furthermore, oligoclonal CD4+ T cell expansion has been suggested to contribute to the pathogenesis of obliterative bronchiolitis." (PMID 17610738, 2007). "Future studies will address the question if expression of CD40L is unique for CD4+CD28− T cells in bronchiolitis obliterans syndrome or not." (PMID 25834833, 2015). "Notably, the increase in T cells was characterized by a prominent shift toward a higher CD4:CD8 T cell ratio, which some authors have previously correlated with OB (obliterans bronchiolitis) in lung transplant recipients." (PMID 18042282, 2007).
Osteopenia (8 papers, 2013 to 2025). Osteopenia is a term to define bone density that is not normal but also not as low as osteoporosis. "Patients with osteopenia/-porosis yielded a higher prevalence of senescent CD4+CD28− T-cells than individuals with normal BMD, in the RA, as well as in the non-RA cohort." (PMID 29472917, 2018).
otitis media (8 papers, 2006 to 2025). Inflammation of the anatomical structures of the middle ear, which is most often caused by an infectious process. "Our findings regarding the importance of CD4+ T cells has a clinical correlation, as it has been shown that reduced functional CD4+ T-cell help is associated with susceptibility to recurrent otitis media in children." (PMID 24408968, 2014). "The association between HL and low CD4 cell count may be due to the accumulative damage to the TM and middle ear by recurrent episodes of otitis media, which was present in our study in patients with HL." (PMID 40041248, 2025). "The relationship between clinical stage of the HIV infection, CD4+ lymphocyte count and otitis media was investigated by some authors." (PMID 17143430, 2006).
papillary thyroid carcinoma (8 papers, 2014 to 2024). "In contrast, French and collaborators demonstrated that the presence of regulatory T lymphocytes (CD4+ FoxP3+) was greater in metastatic lymph nodes and was related to the aggressiveness of papillary carcinoma." (PMID 38913547, 2024). "Previous studies showed that a greater presence of regulatory T lymphocytes (FOXP3+) and double-negative T lymphocytes (T CD3+ CD4− CD8−) was associated with papillary carcinoma compared to Hashimoto's thyroiditis." (PMID 38913547, 2024). "Papillary thyroid cancer infiltrating T cells consisted of CD3+ cytotoxic T cell, CD8+ cytotoxic cell, and CTLA4+ and CD4+ Treg cells." (PMID 34805166, 2021).